ENSG00000297385 (novel transcript)
Gene: Long non-coding RNA gene on chromosome 5 (151,696,646 to 151,697,450, forward strand). Ensembl gene ENSG00000297385.
Gene Ontology:
Biological process: RNA processing
Cellular component: nucleolus